VNN3P (vanin 3, pseudogene )
Synonyms: HSA238982; VNN3
Gene: Long non-coding RNA gene on chromosome 6 (132,722,784 to 132,736,935, reverse strand). Ensembl gene ENSG00000293493.
Diseases named in the same sentence as VNN3P in open-access papers:
VNN3P is named in the same sentence as 2 diseases in open-access papers, as found by Europe PMC text mining. Sharing a sentence is not in itself a finding about the gene and the disease.
VNN3P shares sentences with these, for which no sentence is quoted: acute graft versus host disease (1 paper); clear cell renal cell carcinoma (1).